ADAMTS18 (ADAM metallopeptidase with thrombospondin type 1 motif 18)
Diseases named in the same sentence as ADAMTS18 in open-access papers (continued):
Sharing a sentence is not in itself a finding about the gene and the disease.
colon tumors (3 papers, 2012 to 2024). "Several studies have suggested the association between ADAMTS18 gene mutation (and inactivation) and colon cancer." (PMID 28145888, 2017). "To investigate how ADAMTS18 exerts its effect on colorectal cancer as well as the involved molecular events, we generate Adamts18 gene knockout (KO) mice and demonstrate that ADAMTS18 deficiency creates a tumor-promoting microenvironment for colon tumor formation in mice." (PMID 28145888, 2017). "Moreover, increased p38MAPK and ERK1/2 activities were detected in colon cancer cells from Adamts18-deficient mice." (PMID 28145888, 2017). "A comprehensive mutation study identified two missense mutations (R382K and K455T, both located in the catalytic region of metalloproteinases) in ADAMTS18 in colon cancer." (PMID 38482210, 2024). "Taken together, the down-regulation of ADAMTS18 promotes colon cancer development and progression by promoting Wnt/β-catenin and p38 MAPK/ERK1/2 signaling pathways." (PMID 38482210, 2024). "In the AOM/DSS-induced colitis-associated colon cancer (CAC) mouse model, ADAMTS18 gene deletion promotes cancer cell proliferation and inhibits cancer cell apoptosis." (PMID 38482210, 2024). "Consistent with the changes in colon tumor burden, the number of cells expressing Ki-67 was significantly more in colon tumors from Adamts18 KO mice in comparison to WT tumor cells [Ki-67 positive cells (%), WT vs. KO, 50.8 ± 12.9 vs. 72.7 ± 9.2; P = 0.003]." (PMID 28145888, 2017). "We didn't find significant difference in microvessel densities of colon tumors and the expression of Adamts1, 8, 12 which were reported involved in angiogenesis between Adamts18 KO mice and WT littermates." (PMID 28145888, 2017). "Likewise, the results of qRT-PCR showed the expression of its downstream target genes cyclinD1 and c-myc mRNA were significantly increased in the colon cancer cells of Adamts18 KO mice relative to WT littermates." (PMID 28145888, 2017). "However, the exact role of ADAMTS18 in colon cancer progression has not been reported." (PMID 28145888, 2017).
colorectal cancer (3 papers, 2017 to 2025). A primary or metastatic malignant neoplasm that affects the colon or rectum. "Here we generated an Adamts18-deficient mouse strain as an in vivo model to investigate the role of ADAMTS18 in the pathogenesis of colorectal cancer." (PMID 28145888, 2017). "It has been demonstrated that ADAMTS18, as a novel cancer regulator, was vital to colorectal cancer pathology." (PMID 33063817, 2020). "ADAMTS18 is a novel tumor suppressor and is critical to the pathology of human colorectal cancer." (PMID 28145888, 2017).
Knobloch syndrome (3 papers, 2013 to 2025). "This study identified, in the analyzed patient, a homozygous missense mutation in the ADAMTS18 gene, which was recently linked to Knobloch syndrome, a rare developmental disorder that affects the eye and the occipital skull." (PMID 23356391, 2013). "Importantly, the results of our ADAMTS18 knockdown experiment in medaka provide for the first time in vivo functional support to the pathogenic role of this gene in Knobloch syndrome as well." (PMID 23356391, 2013).
gastric cancer (2 papers, 2015 to 2025). A primary or metastatic malignant neoplasm involving the stomach. "In addition, several studies have revealed that the ADAMTS9 and ADAMTS18 gene promoters are also hypermethylated in gastric carcinoma." (PMID 25936341, 2015).
lung carcinoma (2 papers, 2024 to 2025). "For example, high expression of ADAMTS18 in lung cancer is positively correlated with high overall survival (OS) in -stage patients." (PMID 38482210, 2024). "ADAMTS18 has also been illustrated to increase lung cancer cell sensitivity to cisplatin by suppressing the EGFR/AKT signaling pathway." (PMID 38482210, 2024). "ADAMTS18 not only reverses the resistance of ccRCC to sunitinib and axitinib in combination with curcumin but also independently increases the sensitivity of lung cancer cells to cisplatin." (PMID 38482210, 2024). "ADAMTS18 was found to inhibit the proliferation, migration, and invasion of lung cancer cells and to block lung cancer cells in the G0/G1 phase, suggesting that ADAMTS18 itself has a tumor-suppressing effect." (PMID 38482210, 2024). "Previous data showed that ADAMTS18 increases the sensitivity of lung cancer cells to cisplatin, thereby improving patient survival to some extent." (PMID 38482210, 2024). "Furthermore, the mechanism by which ADAMTS18 increases the sensitivity of lung cancer cells to cisplatin is that ADAMTS18 acts as an inhibitor of epidermal growth factor receptor/protein kinase B (EGFR/AKT) signaling antagonist." (PMID 38482210, 2024).
malaria (2 papers, 2023 to 2025). Malaria is a serious and sometimes fatal disease caused by a parasite that commonly infects a certain type of mosquito which feeds on humans. "Candidates were validated in plasma samples from a cohort of pediatric patients with malaria from Mozambique, resulting in the identification of several markers with capacity to distinguish uncomplicated from severe malaria, the most potent being the metallopeptidase ADAMTS18." (PMID 37788095, 2023). "The biological function of the 3 candidate biomarkers, ADAMTS18, ANGPTL4, and INHBE, has not been extensively characterized, and they have not been described before in the context of malaria." (PMID 37788095, 2023).
osteoporosis (2 papers, 2016 to 2025). A condition of reduced bone mass, with decreased cortical thickness and a decrease in the number and size of the trabeculae of cancellous bone (but normal chemical composition), resulting in increased fracture incidence. "Single nucleotide polymorphisms in ADAMTS18 were associated with reduced bone mineral density, which determines susceptibility to osteoporosis in three distinct ethnic groups; and the C-terminus of ADAMTS18 was shown to induce platelet thrombus fragmentation." (PMID 27638769, 2016). "Again, in line with the current findings on ADAMTS18, these data together suggest a pivotal role for ADAMTS18 in maintaining bone health in athletes and serving as a potential therapeutic target for osteoporosis." (PMID 40656995, 2025).
pancreatic carcinomas (2 papers, 2017 to 2024). "For example, the methylation frequencies of ADAMTS18 in breast, colorectal, and pancreatic cancers are 70.8%, 49%, and 39%, respectively, which may explain the mechanism of action of ADAMTS18 in different types of cancers." (PMID 38482210, 2024).
Retinal dystrophy (2 papers, 2013 to 2025). Retinal dystrophy is an abnormality of the retina associated with a hereditary process. "Our data indicate that different mutations in the ADAMTS18 can be linked to the pathogenesis of different eye disorders and contribute to shed further light on the molecular mechanisms underlying the complexity of inherited retinal dystrophies." (PMID 23356391, 2013).
anemia (1 paper, 2023). A reduction in the number of red blood cells, the amount of hemoglobin, and/or the volume of packed red blood cells. "ADAMTS18 and ANGPTL4 were also correlated with acidosis and severe anemia." (PMID 37788095, 2023).
Arthritis (1 paper, 2013). Inflammation of a joint. "ADAMTS18 belongs to the ADAMTS family of extracellular proteases, which are zinc-dependent metalloproteinases that play an important role in both normal and pathological events, and especially in connective tissue organization, coagulation, inflammation, arthritis, angiogenesis, and cell migration." (PMID 23593441, 2013).
cervical carcinoma (1 paper, 2024). A carcinoma arising from either the exocervical squamous epithelium or the endocervical glandular epithelium. "In addition, low expression of ADAMTS18 in cervical cancer is positively associated with high tumor stage, positive lymph node metastasis, distant metastasis, short OS, and disease-free survival (DFS)." (PMID 38482210, 2024).
ciliopathy (1 paper, 2023). A genetic disorder of the cellular cilia or the cilia anchoring structures, the basal bodies, or of ciliary function. "ADAMTS18 and CRELD1 were both linked to heterotaxy/ciliopathy." (PMID 36929416, 2023).
colitis (1 paper, 2017). Inflammation of the colon. "Western Blotting analysis further confirmed that TNF-α was increased but IL-4 was decreased in colitis tissues of Adamts18 KO mice when compared to those of WT control." (PMID 28145888, 2017). "In DSS-induced colitis model, Adamts18 KO mice showed severe bloody stools and suffered from significant body weight loss from day 6 compared to WT littermates (day 6: WT vs. KO, 94.5 ± 3.8% vs. 90.5 ± 3.2%, P = 0.048; day 7: WT vs. KO, 90.3 ± 3.6% vs. 84.5 ± 2.6%, P = 0.004)." (PMID 28145888, 2017). "Adamts18 KO mice and the age- and sex-matched wild-type littermates were injected with the procarcinogen azoxymethane (AOM) and then received three rounds of dextran sodium sulfate (DSS) exposure to elicit colitis." (PMID 28145888, 2017).
gastric adenocarcinoma (1 paper, 2024). "In gastric adenocarcinoma, ADAMTS18 is positively correlated with tumor differentiation, lymph node metastasis, TNM stage, short OS." (PMID 38482210, 2024). "Studies on immunization with gastric adenocarcinoma gene vaccines have shown that upregulation of ADAMTS18 enhances the infiltration of CD8+ T cells, CD4+, macrophages, and neutrophils, which induces an immune response and positively correlates with the immune infiltration of DCs." (PMID 38482210, 2024). "Notably, ADAMTS18 was found to be upregulated in gastric adenocarcinoma and pancreas adenocarcinoma tissues, suggesting that ADAMTS18 also has oncogenic activity." (PMID 38482210, 2024).
Infertility (1 paper, 2016). "Thus, Adamts18 is essential in the development of distinct tissues and the new mouse strain is likely to be useful for investigating ADAMTS18 function in human disease, particularly in the contexts of infertility and carcinogenesis." (PMID 27638769, 2016).
lymph node metastasis (1 paper, 2023). "There was a significant association between ADAMTS18 methylation and lymph node metastasis." (PMID 37240178, 2023).
lymphoma (1 paper, 2017). A malignant (clonal) proliferation of B- lymphocytes or T- lymphocytes which involves the lymph nodes, bone marrow and/or extranodal sites. "Further, similar to our findings, the positive correlations between E-cadherin (CDH1) and ADAMTS18 mRNA levels were found in human lymphoma samples, which may reflect the requirement of ADAMTS18 for E-cadherin processing in the cells." (PMID 28145888, 2017).
microphthalmia (1 paper, 2025). Congenital or developmental anomaly in which the eyeballs are abnormally small. "Ocular defects seen in Adamts18 knockout mice include breaks in the lens capsule resulting in extrusion of material, but microphthalmia, microcornea and retinal anomalies were not seen." (PMID 41011222, 2025).
pancreas adenocarcinoma (1 paper, 2024). "The immune positivity of ADAMTS18 was also found to be higher in metastatic lymph nodes than in non-metastatic lymph tissue in pancreas adenocarcinoma." (PMID 38482210, 2024).
renal carcinoma (1 paper, 2024). A carcinoma arising from the epithelium of the renal parenchyma or the renal pelvis. "Therefore, the immune microenvironment plays a role in UB morphology, and a previous study of renal cancer by our research team revealed that the ADAMTS18 gene could play an antitumor role in renal cancer by regulating the infiltration status of immune cells." (PMID 38397998, 2024).
renal cell carcinoma (1 paper, 2024). "Curcumin is capable of inhibiting the proliferation of renal cell carcinoma by regulating the miR-148/ ADAMTS18 axis via the suppression of autophagy in vitro and in vivo." (PMID 39795863, 2024).
retinal diseases (1 paper, 2013). "This study reveals that mutations in the ADAMTS18 gene can cause a broad phenotypic spectrum of eye disorders and contribute to shed further light on the complexity of retinal diseases." (PMID 23356391, 2013).
Sepsis (1 paper, 2023). Sepsis is defined as life-threatening organ dysfunction caused by a dysregulated host response to infection. "In particular, ADAMTS18, a metallopeptidase, may be also present in sepsis patients, where this family of proteins is upregulated." (PMID 37788095, 2023).
Ureteral obstruction (1 paper, 2024). Obstruction of the flow of urine through the ureter. "Previous studies by our team confirmed the role of the ADAMTS18 gene in renal chronic fibrosis in an in vitro cell line and confirmed the reversal of obstructive fibrosis via overexpression of the ADAMTS18 gene in a rat model with ureteral obstruction." (PMID 38397998, 2024).
tumor (25 papers, 2009 to 2025). "We thus sought to establish the association between ECM alterations caused by ADAMTS18 deficiency and tumor behavior." (PMID 38287441, 2024). "We found that the inhibition of tumor migration and invasion by ADAMTS18 are associated with deregulation of AKT and NF‐κB signaling pathway, in which AKT pathway was in line with the findings in ADAMTS9, another member of the same subgroup 6." (PMID 28503860, 2017). "ADAMTS18 is implicated in numerous processes such as tumor suppression, cell migration, and immune response." (PMID 22216092, 2011). "This suggests Adamts18 deficiency promotes proliferation of tumor cells." (PMID 28145888, 2017). "In recent decades, previous studies have made breakthroughs in the tumor suppressor activity and mechanisms of ADAMTS18." (PMID 38482210, 2024). "With the assistance of ADAMTS18, the relationship between mechano-signaling and cytoskeletal assembly is established to regulate the malignant phenotype of tumor cells." (PMID 38482210, 2024). "In these tumor-bearing mice, spontaneous tumors appeared significantly earlier in Her2t/w/Adamts18−/− mice than in Her2t/w/Adamts18+/+ mice." (PMID 38287441, 2024). "To date, there is a gap in clinical targeted drug studies for ADAMTS18, and we will provide examples of ADAMTS18 in combination with cisplatin and curcumin to provide new references for tumor therapy." (PMID 38482210, 2024). "Here, we will focus on the latest research advances to systematically introduce the biological functions and mechanisms of ADAMTS18 in tumorigenesis and development, as well as its close connection with tumor diagnosis and prognosis." (PMID 38482210, 2024). "As ADAMTS18 has been shown to cleave FN, this ECM component accumulates in ADAMTS18 KO tumours, resulting in integrin dependent ERK and AKT activation." (PMID 38948119, 2024). "In this context, the large number of tumor cells and mouse tumor models have been established and analyzed for the function of ADAMTS18, including cell proliferation signals, cell death patterns, cell migration, and invasion." (PMID 38482210, 2024). "In PAAD, the levels of DNA methylation at tumour suppressor genes such as ADAMTS18 and HPP1 genes in cancer tissues are also higher than that in normal tissues." (PMID 36811277, 2023). "Western Blotting showed phosphorylated forms of both p38MAPK and ERK1/2 were significantly increased in tumor cells of Adamts18 KO mice when compared with WT littermates." (PMID 28145888, 2017). "Since some ADAMTSs (e.g. ADAMTS-1 and -8) have anti-angiogenic activities that contribute to the inhibition of cancer development, we thus examined the relevance of Adamts18 with tumor angiogenesis." (PMID 28145888, 2017). "Further investigation of the exact mechanism by which ADAMTS18 can act on AKT during the course of multistep tumor progression is needed." (PMID 28503860, 2017). "Adamts18 KO mice demonstrated higher tumor incidence rates and more tumor numbers than WT littermates (macroscopic polyps, WT vs. KO, 71% vs. 100%; tumor numbers, WT vs. KO, 1.5 ± 1 vs. 6.5 ± 1.9; n = 7/group, P = 0.0026)." (PMID 28145888, 2017). "Since ADAMTS18 is one of these genes located around 16q23 region, it has been studied as a potential tumor suppressor gene." (PMID 28145888, 2017). "This phenomenon highlights the importance of tumor-specific ADAMTS18 gene hypermethylation in the tumorigenesis of ccRCC." (PMID 25569086, 2015). "This is the first study to estimate the prevalence of ADAMTS18 gene methylation in a large set of ccRCC tumor samples." (PMID 25569086, 2015). "Most importantly, the mRNA expression levels of ADAMTS18 in 10 ccRCC tumor samples were significantly lower than those in their adjacent normal tissues (p = 0.014)." (PMID 25569086, 2015).